CD44 (CD44 molecule (IN blood group))
Diseases named in the same sentence as CD44 in open-access papers (continued):
Sharing a sentence is not in itself a finding about the gene and the disease.
colon carcinoma (continued). "Galectin-9 interacts with cell surface adhesive molecule CD44 and this interaction inhibits the complex formation of CD44 with hyaluronic acid, which consequently attenuates metastatic dissemination of melanoma and colon cancer cells." (PMID 36873388, 2023). "It has been shown that CD44 plays a key role in colon cancer invasion." (PMID 36831488, 2023). "Similarly, MSC-like cells isolated from human colon cancer can also secrete IL-6 and enhance the expression of stem cell marker CD44 in HCT-116 and HT-29 cells through the Notch signaling pathway." (PMID 37124519, 2023). "Furthermore, using the GEPIA web tool, we found that the mRNA expression of KITENIN positively correlated with that of ß-catenin, c-Myc, cyclin D1, CD44, and HIF-α levels in colon cancer, in which their overexpression is associated with poor survival." (PMID 37553596, 2023). "Core 1-mediated disruption of CD44 O-glycosylation allows truncated CD44 in human colon cancer cell lines to be secreted into the extracellular environment via microvesicles; thus, exosome CD44 may be a potential vehicle for aberrant O-glycosylation." (PMID 35936713, 2022). "In addition, we saw increased expression of stemness markers and putative markers of colon cancer–initiating cells such as CD44 (Cd44) and CD133 (Prom1)." (PMID 35947664, 2022). "CD44 is an adhesion and anti-apoptotic molecule that is highly expressed in colon cancer." (PMID 35733095, 2022). "Likewise, CDP0857 treatment of various colon cancer lines decreased levels of the cell-surface proteins CD44 and CD133, which are CSC markers." (PMID 35453609, 2022). "However, OXA also reduced the expression of CD24 and CD44, which are specific surface markers for colon cancer stem cells, while TP5 mildly enabled OXA to exert an inhibitory effect on stem cell stemness." (PMID 35242031, 2022). "Similarly, osteopontin (OPN), expressed by tumor cells in colon cancer, is an immune checkpoint that is a ligand for CD44 on the surface of T cells, and by binding to CD44 can effectively suppress T cell activity, resulting in enhanced cancer immune tolerance." (PMID 35590394, 2022). "To investigate CPD0857 activity in colon cancer lines, we examined and quantified CD44 and CD133 expressions in various colon cancer lines, such as CCD-18Co, HCT15, HT-29, (Caco2, SW480, SW480APC15, HCT116 (HAE6) MT, HCT116 HAE6) WT, D-K-Ras WT, SW480APC38, HCT116 and D-K-Ras MT." (PMID 35453609, 2022). "Moreover, the T-f and A-f fractions were shown to significantly decrease the level of CD44 expression, which also confirmed the ability of these fractions to promote differentiation in colon cancer cells." (PMID 35631686, 2022). "The interaction of E-selectin with CD44 expressed by LS174T colon carcinoma cells was originally hypothesized based on CD44 immunoreactivity with the HECA-452 antibody, which detects sialofucosylated oligosaccharides (a group to which E-selectin binds)." (PMID 34829810, 2021). "Therefore, primary colon carcinoma (M-24) cells expressed the CSC (CIC) markers CD44 and CD133 in this study." (PMID 34641226, 2021). "In addition, CD44 protein changed methionine-pool metabolites including spermidine and spermine, and reactive cysteine persulfides in human colon cancer cells, promoting cancer growth." (PMID 33780455, 2021). "However, even though SNU-C5 human colon cancer cells expressed CD44 protein, 89Zr-anti-CD44 uptake in SNU-C5 tumors was disappointingly low." (PMID 33594192, 2021). "CD44 is a surface marker of breast, gastric, and colon cancer stem cells, and CD44 is closely related to the cell adhesion-mediated drug resistance of MM cells, which suggests that CD44 may also serve as a marker of MM stemness." (PMID 34298738, 2021). "In addition, knockdown of either PIK3CA or SLC6A6 resulted in decreased expression of α-SMA and increased expression of E-cadherin along with decreases in CD44, CD133, and Nanog, indicating a loss in markers for EMT and colon cancer stem cells." (PMID 34571860, 2021).
colon carcinoma (continued). "Thus, the therapeutic method to eradicate colon cancer should focus on eliminating CD133+CD44+ CCSCs." (PMID 33819194, 2021). "PRDX2 overexpression was shown to be closely correlated with CD133+CD44+ CCSCs in colon cancer." (PMID 33819194, 2021). "Previous study showed that SPHK1 may exert metastatic and invasive effects by upregulation of CD44 (hyaluronan receptor) expression through the ERK signaling pathway in colon cancer cells." (PMID 33506044, 2021). "In addition, xenotransplanted mice with cancer cells bearing stem cell surface markers (ESA+ /CD44+ /CD166+) derived from patients with colon carcinoma showed an increased resistance to irinotecan." (PMID 32503256, 2020). "The down-regulation of miR-203 in CD44+ cells derived from colon carcinoma (HCT-15 and HCT-116) could inhibit the stemness of CRC cells by targeting Snail signalling." (PMID 32503256, 2020). "Proteomic analysis of EVs isolated from colon carcinoma cell‐derived organoids even revealed a distinct population of exosomes according to EpCAM expression and showed a colocalization of EpCAM with CD44 and claudin 7, proteins that are known to promote tumour progression." (PMID 33343836, 2020). "Higher expression of CD133 and CD44 of both cell populations and a higher number of formed spheres in comparison to well-established colon carcinoma cell lines HT-29 and HCT-116 validated the existence of a subpopulation with potential stem cell-like phenotype." (PMID 32927768, 2020). "Moreover, we also provide several lines of evidence to confirm that CD133+CD44+ cells are responsible for the metastasis of colon cancer, another critical functional characteristic of LT-TICs." (PMID 32729895, 2020). "These cell subpopulations could be distinguished on the basis of expression of CD133 and CD44 that are well established markers for stemness characteristics in colon cancer." (PMID 32423158, 2020). "In the present study, our data showed that CD133+CD44+ cells resident in the colon tumor mass are able to generate serial xenografts showing virtually unlimited growth potential, which is in line with the critical functional feature that LT-TICs maintain tumor formation in serial xenotransplants." (PMID 32729895, 2020). "Besides Sox2 and ALDH, expression of several other surface proteins, such as CD44, CD133, Lgr5, CD24, EpCAM and ABCG2, has been associated with stemness features in the context of colon cancer." (PMID 32927726, 2020). "The HA provided tumor-targeted delivery by binding to CD44 on colon cancer cells." (PMID 32102476, 2020). "The release of soluble ECD of CD44 into the serum may be an indicator of tumor progression and metastasis in colon cancer." (PMID 33062960, 2020). "In the present study, based on the methods for isolating stem cells, we isolated and identified a subset of CD133+CD44+ cells that may be enriched in LT-TICs of colon cancer for the first time." (PMID 32729895, 2020). "In several KRAS mutated cancers, the CD44 molecule associates with ALCAM/CD166 promoting an aggressive phenotype that predicts worse outcome and increased risk of liver and lung metastasis (e.g., colon cancer)." (PMID 31552188, 2019). "Moreover, the importance of CD44 in colon cancer has been shown to affect tumorigenicity and stemness, and be of clinical and prognostic importance." (PMID 30548174, 2019). "Increased CD44 expression has been shown to enhance CSC properties in colon cancer cells." (PMID 30548174, 2019). "In this article, as a potential mechanism for its radio- and chemosensitizing activity, we report that RRx-001 targets CD133+/CD44+ cancer stem cells from three colon cancer cell-lines, HT-29, Caco-2, and HCT116, and inhibits Wnt pathway signalling with downregulation of c-Myc." (PMID 29805745, 2018).
colon carcinoma (continued). "Previous reports showed that the increased level of miR-34a was linked to the suppression of the generation of cancer stem cells in prostate and pancreatic cancer via directly down-regulating CD44 expression, in agreement with our observation in colon cancer cells." (PMID 30005681, 2018). "The other membrane marker used for the identification of colon cancer stem cells is CD44, a class I transmembrane glycoprotein acting as a receptor for constituents of the extracellular matrix, such as hyaluronic acid, and a downstream target of the Wnt/β-catenin pathway." (PMID 29652830, 2018). "Fibronectin EDA may promote tumorigenesis by sustaining the properties of CD133+/CD44+ colon cancer cells." (PMID 29747682, 2018). "In fact, it was shown that colon cancer cell lines contain cancer stem cell populations that can be enriched by the use of an in vitro, Matrigel-based differentiation assay together with selection for the expression of CD44 and CD24 cell surface markers." (PMID 29652830, 2018). "Furthermore, their clone formation capability and the percentage of colon cancer stem cell (CD44+CD133+ population) within colon cancer cells were also reduced by rhIL-37." (PMID 28467774, 2017). "It has been reported that nuclear translocation of CD44 can reprogram colon cancer cells into CSCs." (PMID 27894081, 2017). "Furthermore, their clone formation capability and the percentage of colon cancer stem cell (CD44+CD133+ population) within colon cancer cells were also reduced by IL-35." (PMID 29069729, 2017). "In other words, the levels of CD166 and CD44 were much higher in colon cancer spheroid cells." (PMID 29110645, 2017). "As for CD44, Lgr5 is a Wnt-regulated gene, a CSC marker required for the maintenance of CRC-derived liver metastasis and specifically associated to 5FU chemoresistance in colon cancer patients." (PMID 29354056, 2017). "In addition, the expression of endogenous miR-140 was significantly elevated in CD133(+hi)CD44(+hi) colon cancer stem-like cells that exhibit slow proliferating rate and chemoresistance." (PMID 28573140, 2017). "Therefore, CD133+CD44+CD24loALDHhimay further define a 5-FU-resistant human colon carcinoma stem cell phenotype from the CD133+CD24lo cells, which also requires further studies." (PMID 27659530, 2016). "Nevertheless, CD133 and CD44 could be strong biomarkers for the identification of CSCs in colon cancer." (PMID 26840024, 2016). "CD44 and Lgr5 has also been shown to be a marker of CSCs in colon cancer." (PMID 27894099, 2016). "In this study, we confirmed CD44 was strikingly opposite to CD4 in colon cancer." (PMID 27323782, 2016). "The heatmaps of CD44 mRNA in colon cancer were strikingly opposite to CD4 and CD74." (PMID 27323782, 2016). "Notably, CD44 and CD66c showed functional properties in colon cancer cells, however, by contrast, the functional importance of CD133 appeared to be marginal." (PMID 25624884, 2015). "Similarly, single CD44+ colon cancer cells have been shown to form spheres in serum-free sphere media and have been used to establish xenograft tumor models in vivo." (PMID 25941936, 2015). "Lee and colleagues found that the standard CD44 expressed in the nucleus could reprogram colon cancer cells line to CSCs under suspension culture, CD44 could integrate with STAT3 and gp130 after reprogramming and function as a transcription factor complex." (PMID 26540347, 2015). "It has also been shown that CD133/CD44 expressing colon cancer cells express EMT markers." (PMID 24760019, 2014). "Using immunohistochemistry, we found that CD44 (95%) and CD24 (91%) were expressed abundantly in human colon cancer glandular tissues, whereas CD44 (35%) and CD24 (20%) were undetected or weakly detectable in human adjacent noncancerous colon glandular tissues." (PMID 24696849, 2014). "Furthermore, several studies have demonstrated that CD44 is a robust marker with functional importance for colon cancer stem cells." (PMID 24009708, 2013).
colon carcinoma (continued). "CD44, in particular, is a well-known marker for colon cancer stem cells." (PMID 23800986, 2013). "CD44 is the major functional fibrin receptor on colon carcinoma cells." (PMID 23056168, 2012). "CD44 could be detected on all colon cancer cell lines investigated with a mean expression of 74.22 ± 15.73%." (PMID 22433494, 2012). "In addition to CD133, CD166, CD44 and EpCAM, a potential colon cancer stem cell marker is proposed to be the somatic intestinal stem/progenitor cell marker Lgr5." (PMID 21318087, 2011). "Isolation of CSCs from colon carcinomas can be accomplished by selection of a subpopulation of tumor cells based on expression of one or multiple cell surface markers associated with cancer stemness, like CD133, CD44, CD24, CD29, CD166 and Lgr5." (PMID 21311095, 2010). "Furthermore, the expression of miR-215 was elevated in CD133+HI/CD44+HI human colon cancer stem cells, leading to their slow proliferation rate and allowing them to resist the damage caused by chemotherapeutic agents." (PMID 20433742, 2010). "CD133 has been reported to be a presumed colon cancer stem cell marker, even if this function is now challenged, and CD44 has been more convincingly described as an informative marker of colon cancer stem cells in both primary tumours and xenografts." (PMID 19603013, 2009). "It is less likely that a known marker for colon cancer stem cells, such as CD44, CD166, EpCAM, and Lgr5, has the potential just like Pten-related pathway in leukemia, which could distinguish hematopoietic stem cells from leukemia-initiating cells." (PMID 19583834, 2009). "The aim of the present study was to assess whether CD44 can be regulated in high metastatic colon cancer cell line expressing high levels of this polymorphic glycoprotein and whether this regulation could affect metastasis." (PMID 12439723, 2002). "Thus, as it has been partially shown in colon cancer, CD44 isoform 4 can play an anti-tumor role during the initial malignant transformation but may later benefit metastasis formation." (PMID 38106992, 2023). "Furthermore, CD44-Doxil exhibited higher doxorubicin concentrations within tumor cells as well as excellent antitumor efficacy and improved therapeutic effect compared with Doxil-treated C-26 colon cancer mice." (PMID 37465582, 2023). "Additionally, the level of phosphorylated transmembrane tyrosine kinases (e.g., ERBB2) and its interactions with other signalling factors in colon cancer cell lines may depend on endogenous HA and CD44 interaction." (PMID 37445716, 2023). "Similarly, mammalian galectin-9 suppressed binding of HA to CD44 on melanoma and colon cancer cell lines resulted in suppression of both attachment and invasion of tumor cells by inhibiting their binding of adhesive molecules to ligands on vascular endothelium and the extracellular matrix." (PMID 36032131, 2022). "Importantly, the crucial stem cell function-inducing role of PRDX2 in CD133+CD44+ CCSCs may have important clinical implications for eradicating colon cancer." (PMID 33819194, 2021). "Furthermore, CD44, another P-selectin ligand, has been shown in several colon cancer studies." (PMID 34439397, 2021). "Moreover, SLCO4A1-AS1, miR-150-3p and/or SLCO4A1 were overexpressed or depleted in colon cancer cells to detect their effects on migration, invasion, sphere formation, apoptosis and tumorigenesis abilities of colon cancer stem CD133+CD44+ cells using both in vitro and in vivo assays." (PMID 33958701, 2021).
colon carcinoma (continued). "In addition, our results indicate that the root cause of the chemoresistance of colon cancer may be the higher levels of antioxidant genes involved in antioxidant defense systems and the lower levels of ROS in CD133+CD44+ cells." (PMID 32729895, 2020). "When the Hh pathway was inhibited in HT29 cells with the SMO inhibitor cyclopamine, reduced expression of stemness markers, such as CD44 and CD133, was observed, suggesting that Prdx2 may promote CSC-associated properties in colon cancer via the Hh/Gli1 signaling pathway." (PMID 27894099, 2016). "Therefore, CD133+CD44+CD24lo may represent a subset of human colon CSCs that are responsible for human colon cancer 5-FU resistance." (PMID 27659530, 2016). "Correspondingly, knockdown of CD44 with specific siRNA (small interfering RNA) in human colon cancer cells could dramatically suppresse cell growth and tumor progression in vitro and in vivo, strongly implying a potent regulator of CD44 in the progression of CRC." (PMID 26010608, 2015). "We have also analyzed the radiation sensitivity of the colon cancer cells sorted for CD133high/CD44high and CD133low/CD44low expression, and further investigated the influence of two AKT isoforms (AKT1, AKT2) on CD133 and CD44 expression, including CD44 splice variant isoforms." (PMID 24760019, 2014). "However, no details about the expression of variant exons in CD44 or cancer stem cells in colon cancer are available." (PMID 23800986, 2013). "CD44v6 is a splice variant of CD44 (CD44v) could also bind to OPN and likely promotes cancer cell adherence to the vascular endothelium and the base membranes, then enhances the invasion and metastasis of colonic carcinomas." (PMID 23112867, 2012). "Strikingly, most of the Wnt genes upregulated by HMGA1 in our murine model are also upregulated in human colon cancer, including the WNT effectors, ASCL2, AXIN2, CTNNB1, MYC, EPHB2, CD44, and ETS2 and the WNT receptors, LGR5, LRP5, and LRP6." (PMID 39895630, 2025). "It is reported that CD44 has tumor-processing function and promotes EMT and metastasis of colon cancer cells." (PMID 40695891, 2025). "We employed three colon cancer cell lines (HCT116, HT29, and SW480), each exhibiting varying proportions of CSCs (CD133+/CD44+)." (PMID 40226589, 2025). "Target genes of this pathway, including CD44, CD133, Lgr5, EpCAM and c-Myc, are frequently used as markers of colon cancer-initiating cells." (PMID 40259095, 2025). "Our results confirmed that expressions of CD44 and CD166 were notably higher in resistant colon cancer cells." (PMID 38233377, 2024). "This study revealed that remimazolam promoted the cell-cycle progression and proliferation of HCT8 colon cancer cells by upregulating CDK1, PTTG1, CDC25C, CDK4, PLK1, PCNA, Ki67, RNASEH2B, FEN1, Cyclin D1,CD44 CDK2, CDKN3, CDC45, IQGAP3, and CDK6." (PMID 38725628, 2024). "Specifically, colon tumor cells can be tackled by exploiting SPION-enabled molecular targeting (e.g., HA functionalization to bind CD44-overexpressing cells) or pH-promoted release." (PMID 38543324, 2024). "This is consistent with existing literature which reports that PDL1 expression is elevated in CD44+ breast and head and neck squamous cancer stem cells and CD133+ colon cancer stem cells." (PMID 39717106, 2024). "For further analysis, we identified increased expression levels of VEGF-A, CTNNB1, CD44, and MMP7 oncogenic signatures in different colon cancer cell lines." (PMID 36672201, 2023). "To assess the relationship between Piezo1 and CCSCs in colon cancer patients, we evaluated the expression of Piezo1, CD133 and CD44 in the tumor tissues." (PMID 37306789, 2023).